SLC24A2 (solute carrier family 24 member 2)
Description:
Calcium, potassium:sodium antiporter that transports 1 Ca(2+) and 1 K(+) in exchange for 4 Na(+). Required for learming and memory by regulating neuronal Ca(2+), which is essential for the development of synaptic plasticity (By similarity).
Synonyms: NCKX2
Tractability: Antibody: UniProt places it where antibodies can reach, with high confidence; its Gene Ontology location is reachable by antibodies, with high confidence; UniProt predicts a signal peptide or a membrane-spanning region; the Human Protein Atlas places it where antibodies can reach. PROTAC: ubiquitination databases record sites on it.
Gene: Protein-coding gene on chromosome 9 (19,507,452 to 19,789,119, reverse strand). Ensembl gene ENSG00000155886.
Subcellular location: Cell membrane
Subcellular location (Human Protein Atlas): Plasma membrane
Pathways (Reactome):
Transport of small molecules: Sodium/Calcium exchangers
Gene Ontology:
Molecular function: calcium, potassium:sodium antiporter activity; calcium channel activity
Biological process: calcium ion import; calcium ion import across plasma membrane; calcium ion transmembrane transport; intracellular calcium ion homeostasis; monoatomic ion transmembrane transport; potassium ion transmembrane transport; sodium ion transmembrane transport; cellular response to high light intensity; cone photoresponse recovery; long-term synaptic depression; long-term synaptic potentiation; phototransduction; transmembrane transport
Cellular component: plasma membrane; photoreceptor inner segment; membrane
Genetic constraint (gnomAD): Loss-of-function variants: 26 observed, 49.66 expected, observed/expected ratio (o/e) 0.52, 90% interval 0.38 to 0.73. The upper end of that interval is the gene's LOEUF score, 0.73, which puts it in group 2 of 6, group 1 being the genes least tolerant of losing a copy. Missense variants: 799 observed, 799.72 expected, observed/expected ratio (o/e) 1, 90% interval 0.94 to 1.06. Synonymous variants: 340 observed, 291.46 expected, observed/expected ratio (o/e) 1.17, 90% interval 1.07 to 1.28.
Homologues: Orthologues: chimpanzee SLC24A2 (99% identical), macaque SLC24A2 (97% identical), pig SLC24A2 (94% identical), dog SLC24A2 (93% identical), rabbit SLC24A2 (93% identical), guinea pig SLC24A2 (89% identical), mouse Slc24a2 (88% identical), rat Slc24a2 (87% identical), tropical clawed frog slc24a2 (73% identical), zebrafish slc24a2 (60% identical), Drosophila melanogaster Nckx30C (46% identical), Caenorhabditis elegans ncx-5 (39% identical), and 1 more. Paralogues in human: SLC24A1 (56% identical), SLC24A3 (33% identical), SLC24A4 (32% identical), SLC24A5 (27% identical).
Diseases named in the same sentence as SLC24A2 in open-access papers:
SLC24A2 is named in the same sentence as 34 diseases in open-access papers, as found by Europe PMC text mining. Sharing a sentence is not in itself a finding about the gene and the disease. The quoted sentences say what the papers report.
pancreatic ductal adenocarcinoma (3 papers, 2020 to 2022). An infiltrating adenocarcinoma that arises from the epithelial cells of the pancreas. "From these types of analyses, variants in SLC24A2 (NCKX2) were identified that are associated with pancreatic ductal adenocarcinoma and, surprisingly, skin colour variation in a Chinese population." (PMID 36614039, 2022). "SLC24A2, a potassium-dependent sodium-calcium exchanger, were observed in pancreatic ductal adenocarcinoma and were associated with esophageal squamous cell carcinoma prognosis." (PMID 35794546, 2022). "Moreover, alterations in SLC24A2, a potassium-dependent sodium-calcium exchanger, were observed in pancreatic ductal adenocarcinoma." (PMID 33381521, 2020).
bladder cancer (2 papers, 2022 to 2023). "Consistent with previous enrichment analysis of DEGs, SLC24A2 showed the abnormal expression in 17 cancers including bladder cancer (BLCA), prostate cancer (PRAD), and lung cancer (LUAD and LUSC)." (PMID 35601016, 2022). "It is also noteworthy that the DEGs between high- and low- SLC24A2 groups were enriched in T2D and several cancer pathways such as bladder cancer and non-small-cell lung cancer." (PMID 35601016, 2022).
esophageal squamous cell carcinoma (2 papers, 2022). Esophageal squamous cell carcinoma (ESCC) is a type of esophageal carcinoma (EC) that can affect any part of the esophagus, but is usually located in the upper or middle third. "In recent years, SLC24A2 has been found as a tumor microenvironment-related gene to be related to the prognosis of esophageal squamous cell carcinoma." (PMID 35601016, 2022).
retinal disease (2 papers, 2007 to 2022). "SLC24A2, also known as NCKX2, is a sodium/potassium/calcium exchanger of the solute carrier family, which was first reported to be associated with retinal diseases." (PMID 35601016, 2022). "Although variant alleles of the cone SLC24A2 gene have been identified, none of them are definitively associated with a specific retinal disease." (PMID 17286855, 2007).
age-related macular degeneration (1 paper, 2021). Age-related loss of vision in the central portion of the retina (macula), secondary to retinal degeneration. "WEE1, SMC2, HMGB1, RRM2, and POLA1 proteins were also observed to be involved in the progression and invasion of retinoblastoma; SLC24A2 and DTX4 in age-related macular degeneration; and EPHB6, EFNB3, and SHC1 in glaucoma." (PMID 34646884, 2021).
bunyavirus infection (1 paper, 2023). "Moreover, other studies have shown that the infection of bunyavirus RVFV can cause significant upregulation of SLC24A2 and SLCA3, suggesting that bunyavirus infection affect alterations in host ion channels, while details about SFTSV infection need to be further investigated." (PMID 37211158, 2023).
colorectal cancer (1 paper, 2024). A primary or metastatic malignant neoplasm that affects the colon or rectum. "Finally, colorectal cancer cells migration, growth and colony formation assays were performed in RKO cells with the overexpression or knockdown SLC8A3, SLC24A2, SLC24A3, or SLC24A4." (PMID 39006025, 2024).
pan (1 paper, 2022). "Timer and K-M plotters were employed to find the expression and prognosis of SLC24A2 in pan cancer." (PMID 35601016, 2022).
skin changes (1 paper, 2024). "That it is among the top results of our showcase analysis comparing ‘young’ and ‘old’ single cells also suggests the possibility of SLC24A2 being involved in age-related skin changes and warrants further laboratory research." (PMID 38630692, 2024).
tumor (4 papers, 2022 to 2024). "Additionally, voltage-gated ion channels and genes like KCNQ5, KCNV1, ADAMTS14, MPPED1, and SLC24A2 are linked to tumor traits in these tumors." (PMID 39139281, 2024).
infection (3 papers, 2017 to 2023). The state of being infected such as from the introduction of a foreign agent such as serum, vaccine, antigenic substance or organism. "Sodium voltage-gated channel alpha subunit 3 (SCN3A) and two solute carriers SLC24A2 and SLC1A3 were highly altered following infection." (PMID 29085037, 2017). "Sodium voltage-gated channel alpha subunit 3 (SCN3A) and two solute carriers SLC24A2 and SLC1A3 were highly altered following infection, indicating that ion transport could be important in response to infection." (PMID 29085037, 2017).
cancer (2 papers, 2022 to 2024). A tumor composed of atypical neoplastic, often pleomorphic cells that invade other tissues. "The results showed that SLC24A2 played opposite roles in different types of cancers due to the tissue specificity of SLC24A2." (PMID 35601016, 2022). "Taken together, SLC24A2 may link T2D and cancer by influencing the ribosome function of islet β cells and play different prognostic roles in different cancers." (PMID 35601016, 2022). "Interestingly, both DEGs between T2D verse control and SLC24A2-high verse SLC24A2-low enriched in cancer-related pathways." (PMID 35601016, 2022). "That is to say, the shared DEGs imported into WGCNA, as well as SLC24A2, could explain the coexistence of T2D and cancer to some extent." (PMID 35601016, 2022). "That is to say, although SLC24A2 may play different roles in different cancers, they were all closely related to prognosis." (PMID 35601016, 2022). "The association of SLC8A3, SLC24A2, SLC24A3 and SLC24A4 with cancer is still unknown." (PMID 39006025, 2024). "In addition, SLC24A2 was only expressed in islet β cells and showed abnormal expression in 17 kinds of cancers and significantly correlated with the prognosis of 10 kinds of cancers." (PMID 35601016, 2022).
SLC24A2 also shares sentences with these, for which no sentence is quoted: brain ischemia (3 papers); ischemia (2); melanoma (2); Stroke (2); adenoma (1); adrenocortical tumors (1); Cerebral ischemia (1); depression (1); diabetes (1); glaucoma (1); glioblastoma (1); lung carcinoma (1); neurodevelopmental disorder (1); night blindness (1); non-small cell lung carcinoma (1); prostate carcinoma (1); retinitis pigmentosa (1); retinoblastoma (1); small cell lung carcinoma (1); Stillbirth (1); type 2 diabetes mellitus (1); visual disorders (1).